NQO1 (NAD(P)H quinone dehydrogenase 1)
Diseases named in the same sentence as NQO1 in open-access papers (continued):
Sharing a sentence is not in itself a finding about the gene and the disease.
lung adenocarcinoma (10 papers, 2014 to 2025). A carcinoma that arises from the lung and is characterized by the presence of malignant glandular epithelial cells. "The results showed that skin cutaneous melanoma, skin cutaneous melanoma, brain lower grade glioma, lung squamous cell carcinoma, mesothelioma, and lung adenocarcinoma had high expression levels of NQO1 mRNA." (PMID 37583897, 2023). "Our results show that NQO1 differs between genders in lung adenocarcinoma, lung squamous cell carcinoma, liver hepatocellular carcinoma, lymphoid neoplasm diffuse large B-cell lymphoma, kidney renal papillary cell carcinoma, and sarcoma." (PMID 37583897, 2023). "NQO1 protein expression in tumor cells labelled with pan-cytokeratin was quantitatively measured across this early-stage naïve lung adenocarcinoma cohort (I and II) and demonstrated varying levels of NQO1 on an individual cell level." (PMID 36359002, 2022). "Previously, the use with paraquat to induce lung damage had been described in human lung-adenocarcinoma cell lines A549, where Sm reduced toxicity by inducing the expression of the antioxidant genes Nrf2, NQO1, and HO-1 after an exposure of 3 h." (PMID 34564191, 2021). "Therefore, we aimed to address the findings of NQO1 expression across the TME and normal tissue, co-registered with NRF1 and NRF2 in lung adenocarcinoma to expand NRF1 and NRF2 research in NSCLC." (PMID 36359002, 2022).
metabolic syndrome (10 papers, 2015 to 2024). A cluster of metabolic risk factors for CARDIOVASCULAR DISEASES and TYPE 2 DIABETES MELLITUS. "The downstream target of Nrf2, NQO1, has also been implicated in protection against diabetes and metabolic syndrome." (PMID 33298924, 2020). "Associations of NQO1 C609T polymorphisms with components of metabolic syndrome." (PMID 25933176, 2015). "The remaining ten drugged proteins were targeted by compounds indicated for treatment of cancers (CAN2, EPHB1, ERAP1, GSTM3, NQO1, and PVRL4), mitochondrial and muscular disease (NQO1), and metabolic syndrome (CEL)." (PMID 39434187, 2024). "NQO1 has multiple roles in the control of redox processes relevant to several disease states including metabolic syndrome." (PMID 37686150, 2023). "NQO1, a downstream target of Nrf2, seems to play a protective role in metabolic syndrome." (PMID 34947831, 2021). "Moreover, several recent studies have demonstrated the promising roles of NQO1 in protecting against cardiac and vascular damage, as well as related diseases such as dyslipidemia, atherosclerosis, insulin resistance, and metabolic syndrome." (PMID 34947831, 2021). "These observational findings suggest that genetic as well as pharmacological therapeutic strategies targeting NQO1 may have applications in the management of metabolic syndrome." (PMID 34947831, 2021). "Moreover, several recent studies have revealed the promising roles of NQO1 in protecting against cardiovascular damage and related diseases, such as dyslipidemia, atherosclerosis, insulin resistance, and metabolic syndrome." (PMID 34947831, 2021). "Thus, NQO1 may exert protective effects on central adiposity, dyslipidemia, and insulin resistance—representative key features of metabolic syndrome." (PMID 34947831, 2021). "Activated Nrf2 can induce its downstream target genes heme oxygenase 1 (HO-1) and NAD(P)H dehydrogenase (quinone 1) (NQO1), which have antioxidant and anti-inflammatory functions, and which regulate metabolic syndrome." (PMID 34684455, 2021). "Supplying a cellular source of NAD+ that may be critical for inhibiting or preventing metabolic syndrome, binding to mRNA to enhance protein translation, and protecting proteins from proteasomal degradation represent some of the newly discovered functions of NQO1." (PMID 34947831, 2021). "Emerging roles of NQO1 include its function as an efficient intracellular generator of NAD+ for enzymes including PARP and sirtuins which has gained particular attention with respect to metabolic syndrome." (PMID 28883796, 2017).
diabetic nephropathy (9 papers, 2018 to 2025). "Moreover, SFN supplementation conferred oxidative DNA damage protection in streptozotocin-induced diabetic nephropathy by promoting the expression of NQO1 and HO-1." (PMID 35740009, 2022). "In a previous study, AST increased Nrf2 nuclear translocation and enhanced the expression of NAD(P)H, NQO1, superoxide dismutase, and HO-1 in a high glucose-induced diabetic nephropathy injury model, indicating that the Nrf2 pathway may mediate AST’s protective effect." (PMID 38745231, 2024). "Among them, CAT and OGG1 are downregulated, and CASP3, COMT, CYP1B1, DPYD, NQO1, and PTGS1 are upregulated in diabetic kidney disease (DKD) tubuli." (PMID 34367469, 2021).
esophageal squamous cell carcinoma (9 papers, 2012 to 2025). Esophageal squamous cell carcinoma (ESCC) is a type of esophageal carcinoma (EC) that can affect any part of the esophagus, but is usually located in the upper or middle third. "Furthermore, the TT genotype of the NQO1 609C>T polymorphism was associated with reduced NQO1 protein expression in tumor tissues from a subset of GI cancer patients (cardiac carcinoma, gastric adenocarcinoma, esophageal adenocarcinoma, and esophageal squamous cell carcinoma)." (PMID 22272361, 2012). "Another study highlighted the potential of NQO1 (NAD(P)H quinone dehydrogenase 1) as a biomarker for esophageal squamous cell carcinoma." (PMID 40548062, 2025). "For example, in the esophageal squamous cell carcinoma cell lines, the sensitivity of cancer cells to 17-AAG was significantly positively correlated with the NQO1 expression levels." (PMID 37583897, 2023). "In prostate and esophageal squamous cell carcinoma (ESCC), TUG1 directly binds NRF2, thus upregulating its expression at protein level together with its downstream members (HO-1 and NQO1)." (PMID 33287295, 2020).
Hepatic steatosis (9 papers, 2015 to 2025). Steatosis is a term used to denote lipid accumulation within hepatocytes. "Our findings showing elimination of HFD-associated hepatic steatosis and reduction in triglyceride levels in NQO1-Tg livers are consistent with decreased GOT2 activity." (PMID 33298924, 2020). "Our data indicated that CCl4 exposure impaired the Nrf2 antioxidant defense system, worsening oxidative damage in WT mice by downregulating NQO-1 and upregulating HO-1, whereas this system remained intact in ob/ob mice with fatty liver." (PMID 39832399, 2025). "In a study on hepatocyte-specific NFE2L2-upregulation mice with diet-inducing hepatic steatosis, thioredoxin-1, glutathione peroxidase-2, and Nqo1 were increased, and oxidative stress markers decreased." (PMID 35405942, 2022). "The observed improvement in NAD+ metabolism is compatible with greater protection from hepatic steatosis and macrophage infiltration of fat depots by global overexpression of NQO1." (PMID 33298924, 2020). "Histochemical analyses were carried out on fixed liver tissues of mice on HFD diet for 16 weeks to determine the effects of NQO1 overexpression on diet-induced increase in hepatic steatosis." (PMID 33298924, 2020). "If transient forced expression of Nqo1 could enhance NRF2 signaling, NQO1 itself may be the critical mediator for preventing lipodystrophic symptoms like fatty liver." (PMID 37686150, 2023). "To explore whether the alleviation of myricetin on hepatic steatosis was related to the activation of Nrf2 pathway, we measured the protein expression of nuclear and cytosolic Nrf2, as well as NQO1 and HO-1." (PMID 27973423, 2016). "Our results show that NQO1 overexpression leads to improvements in insulin sensitivity and in glucose, lipid and NAD+ metabolism while providing protection from HFD-induced liver steatosis and macrophage infiltration in the adipose tissue." (PMID 33298924, 2020). "Moreover, hepatic NQO1 and HO-1 protein expression was also increased by myricetin, further indicating that myricetin reversed HFD-induced hepatic steatosis through the Nrf2 pathway, favoring enhancement of antioxidant capacity." (PMID 27973423, 2016).
ischemia (9 papers, 2015 to 2023). A hypoperfusion of the BLOOD through an organ or tissue caused by a PATHOLOGIC CONSTRICTION or obstruction of its BLOOD VESSELS, or an absence of BLOOD CIRCULATION. "A study showed that, along with severe ischemic brain damage 3 days after pdMCAO, Nrf2 deficiency destroyed the ischemia-induced increase of antioxidant/detoxification proteins NQO1, HO1, SOD2, and Gpx1." (PMID 30890934, 2019). "Supporting our prior results, immunoblot and immunohistochemistry analyses revealed decreased NQO1 protein expression at day 1 for all ischemia times." (PMID 36139884, 2022). "Compared with S group, the expressions of Nrf2 nucleus protein, HO-1 total protein, and NQO1 total protein in ischemia heart tissues of DEX group, tBHQ group, and tBHQ+DEX group increased significantly (P<0.05) and were also slightly higher compared with those of C group (P>0.05)." (PMID 35959640, 2022). "Notably, Que/mAb GAP43-Exo attenuated oxidative stress-induced ischemia/reperfusion injury and induced the activation of the Nrf2/HO-1 pathway by promoting the nuclear translocation of Nrf2 and upregulating expressions of NQO-1, HO-1, SOD1 and GPx1." (PMID 34001136, 2021). "The obvious increase of Nrf2 downstream antioxidant proteins can be sustained for at least 3 days following ischemia, revealed by the 1.8- to 3.6-fold increase in HO1, NQO1, SOD2, and GPx proteins after pdMCAO." (PMID 30890934, 2019). "Immunofluorescence analysis demonstrated that p-mTOR, Nrf2 and its downstream effectors including NAD(P)H dehydrogenase (quinone 1) (NQO1) and superoxide dismutase 1(SOD-1) protein expression levels were also increased considerably in hypoxic-ischemia rat brain cortex after argon treatment." (PMID 36532733, 2022). "However, our results suggest that activation of the Nrf2/HO-1/NQO1 pathway may respond to chronic HFD-induced oxidative stress and aggravate brain insults such as ischemia, trauma, and seizures." (PMID 26518260, 2015).
liver fibrosis (9 papers, 2013 to 2025). "In proportion, we measured the expression of oxidant related genes in the liver and found that the expression of Ho-1 and Nqo-1 was significantly up-regulated in mice with CCl4-induced liver fibrosis." (PMID 38725842, 2024). "In the “hepatic fibrosis” pathway, eight fibrogenic genes (Pparg, Krt8, H2-Ab1, H2-Aa, Nqo1, Il33, and Ltb) are upregulated, and one gene (Serpina1c) is downregulated." (PMID 33916843, 2021). "Our results showed that TP supplementation alleviated liver morphology, liver function and liver fibrosis; improved oxidative stress parameters; and increased the expression of STAT5b, Nrf2, HO-1 and NQO-1 and decreased the expression of Keap1 in the liver tissues of aged rats." (PMID 31819135, 2019). "In the other study, oral administration of CCl4 to male Sprague-Dawley rats for 6 weeks caused liver fibrosis, as well as a three-fold increase in the liver expression of NQO1 protein, while the amount of hemeoxygenase-1 protein did not change compared to the control." (PMID 40725117, 2025). "For example, in experimental models of liver fibrosis, TGF-β1 suppressed the Nrf2-dependent expression of NQO1 (a major antioxidant enzyme), and the inhibition of Nrf2 activation by dimethyl fumarate inhibited the profibrotic action of TGF-β1." (PMID 39199160, 2024). "Caffeine and ginsenoside Rg1 had been shown to inhibit liver fibrosis through Nrf2-mediated induction of SOD, Nqo1, and GST." (PMID 31933629, 2019). "In contrast, the expressions of GCLC, GCLM, NQO1, and HO-1 in the liver of the model group were significantly increased by YJSB, suggesting that YJSB might improve the antioxidant capacity of the redox system in rats, reduce oxidative stress, and interfere with the development of hepatic fibrosis." (PMID 37229248, 2023).
lymph node metastasis (9 papers, 2014 to 2025). "Correlation analysis revealed that NQO1 overexpression was significantly associated with clinical stage and lymph node metastasis (P < 0.05)." (PMID 39939940, 2025). "High-level NQO1 expression was closely associated with poor differentiation, late-stage, lymph node metastasis and high-risk for HPV infection." (PMID 24912939, 2014). "Similarly, we also analyzed the association between the NQO1 expression and tumor size, lymph node metastasis, and clinical stages of NSCLC." (PMID 25880877, 2015). "Additionally, age, tumor size, differentiation, lymph node metastasis, clinical stage and NQO1 expression were all significantly associated with OS rates of NSCLC patients (P < 0.05)." (PMID 25880877, 2015). "HOXA11-AS expression correlated with the degree of lymph node metastasis, as did NQO1 expression, whereas NQO2 levels showed an inverse correlation." (PMID 36142607, 2022). "More specifically, NQO1 had prognostic value in Luminal A patients with lymph node metastasis (LN(+)), as well in Luminal B patients, and in the total ER(+) patient population." (PMID 28411284, 2017). "The expression rate of the NQO1 protein was correlated with a large tumor size, poor differentiation, lymph node metastasis, late clinical stage, and disease-free and overall survival rates in the NSCLC patients." (PMID 25789070, 2015). "Furthermore, the Cox proportional hazards model highlighted the expression of the NQO1 protein (P = 0.001) and lymph node metastasis (P = 0.035) as significant independent predictors of survival." (PMID 39939940, 2025). "The positive rate of NQO1 protein was related with clinical stage and lymph node metastasis." (PMID 25880877, 2015). "Moreover, multivariate analysis suggested that NQO1 emerged as a significant independent prognostic factor along with tumor size, differentiation, lymph node metastasis and clinical stage in patients with NSCLC." (PMID 25880877, 2015). "The positive rate of NQO1 was related with clinical stage and lymph node metastasis, and the strongly positive rate of NQO1 protein was significantly correlated with tumor size, poor differentiation, advanced clinical stage and lymph node metastasis in NSCLC." (PMID 25880877, 2015). "Moreover, along with clinical stage and lymph node metastasis, multivariate survival analysis demonstrated that NQO1 expression emerged as a significant independent hazard factor for DFS but not for 5-year OS in patients with cervical SCC." (PMID 24912939, 2014). "Comparing the expression of NQO1, NQO2, and HOXA11-AS in lymph node metastasis negative cases (pN0) and positive cases (pN1-3), all showed significant differences." (PMID 36142607, 2022).
lymphoma (9 papers, 1995 to 2025). A malignant (clonal) proliferation of B- lymphocytes or T- lymphocytes which involves the lymph nodes, bone marrow and/or extranodal sites. "The levels of the NQO1 gene were significantly upregulated (p < 0.001) in PBMCs of patients diagnosed with advanced solid tumours and lymphomas, as well as haemodialysis patients suffering from CKD, as analysed by RT-qPCR." (PMID 41109135, 2025). "Lymphoma bearing mice showed reduced expression of phase II antioxidant enzyme NQO1." (PMID 25860911, 2015). "We found that rs1051740 or rs1800566 in EPHX1 and NQO1 were not related with lymphoma susceptibility as previously reported by others." (PMID 23651475, 2013). "This analysis revealed that the combination of the PON1, EPHX1 and NQO1 polymorphisms did not increase the lymphoma risk associated with the PON1 polymorphism alone (OR = 1.7 vs. 1.5)." (PMID 23651475, 2013). "We have studied the prevalence of three functional polymorphisms affecting these genes rs1051740 EPHX1, rs1800566 NQO1 and rs662 PON1 in 215 patients with lymphoma and 214 healthy controls." (PMID 23651475, 2013).
skin cancer (9 papers, 2013 to 2024). "Quinone induced severe oxidative stress rendered Nrf2-deficient mice more prone to skin cancer, while the Nrf2-mediated expressions of NAD(P)H quinone dehydrogenase 1 (Nqo1) and Gst were inhibited." (PMID 39404411, 2024). "It has been reported that the deletion of NQO1 gene makes mice more susceptible to oxidative stress and frequently develop skin tumor upon carcinogen exposure." (PMID 31886179, 2019). "For example, it was reported that dicoumarol and other more specific inhibitors of NQO1 reduce the death of several types of cancer cells, and NQO1-deficient mice exhibit enhanced susceptibility to skin cancers." (PMID 23874855, 2013). "The importance of NQO1 in cancer prevention was supported by the finding that NQO1-null mice are more susceptible to 7,12-dimethylbenz(a)anthracene- and benzo(a)pyrene-induced skin cancer." (PMID 25885439, 2015). "NRF2 and NQO1 are generally recognized to play important roles in cancer prevention and treatment, so they can be targeted for skin cancer." (PMID 35805773, 2022). "As the activation of NRF2 in cancer is two-sided, its functions are more far-reaching than originally envisioned, which presents new challenges and opportunities for targeting NRF2 and NQO1 in skin cancer prevention and treatment." (PMID 35805773, 2022). "This idea is supported by the fact that NQO1 knockout mice develop skin tumor at high frequency when carcinogens are applied." (PMID 31886179, 2019). "It demonstrated that TAX is able to induce the nuclear translocation of Nrf2 and is likely to prevent skin cancer by inducing the expression of HO-1 and NQO1." (PMID 28714938, 2017). "ASX increases DNMT3a expression at low concentrations, but at high concentrations decreases the expression of DNMT1, 3a, and 3b and attenuates NAD(P)H Quinone Dehydrogenase 1 (NQO1) expression via the Nrf2/KEAP1 pathway, reducing cell viability in prostate and skin cancer cells." (PMID 36235389, 2022). "It showed that NAD(P)H:quinone oxidoreductase 1 (NQO1) gene control of C/EBPα against 20S proteasome degradation contributed to the up-regulation of p63 expression and protection for thinning of the epithelium and chemical-induced skin cancer." (PMID 24913332, 2014).
type 2 diabetes (9 papers, 2011 to 2024). "In humans, the NQO1*2 null polymorphism has been associated with increased risk of adverse lipid profiles and Type 2 diabetes." (PMID 37686150, 2023). "In vivo, the kidneys of db/db mice, which are a type 2 diabetes model, were infected with adeno-associated virus to induce NQO1 overexpression." (PMID 35090502, 2022). "In this study, we observed the expression of NQO1 in patients with DN and used type 2 diabetic mice (db/db mice) to investigate the effects of NQO1 overexpression on renal function, oxidative stress and apoptosis in diabetic kidneys." (PMID 35090502, 2022). "One study showed that curcumin supplementation increased NQO-1 levels and reduced plasma malondialdehyde levels in patients with type 2 diabetes, indicating enhanced antioxidant activity via Nrf2 activation, significantly improving oxidative stress markers and overall metabolic profiles." (PMID 39204413, 2024). "Therefore, in order to evaluate the possible mechanisms of the anti-allodynic effects produced by SFN in type 2 diabetic mice, we measured changes in the protein levels of Nrf2, HO-1, NQO1, and JNK in the sciatic nerve from SFN treated db/db mice." (PMID 28700700, 2017). "In the present study, we found that type 2 diabetes significantly down-regulated the expression of renal Nrf-2 and the downstream targets SOD-1, HO-1 and NQO-1, which were remarkably reversed by exposure to LDR, especially at 50 or 75 mGy for both 4 and 8 weeks." (PMID 24651118, 2014).